CDC42 (cell division cycle 42)
Diseases named in the same sentence as CDC42 in open-access papers (continued):
Sharing a sentence is not in itself a finding about the gene and the disease.
prostate carcinoma (continued). "Cyclin D1 expression significantly decreased following Rac1/Cdc42 inhibition in prostate cancer cells." (PMID 24040362, 2013). "By contrast, in TSU-Pr1 cells (also derived from prostate cancer cells) GnRH favors cell migration through mechanisms mediated by the GTPasas Rac1 and Cdc42, and by formation of filipodia and lamellipodia." (PMID 23176180, 2012). "Such a mechanism may be quite restricted by the localization of Rac1 and Cdc42 in androgen-independent prostate cancer cells." (PMID 32092966, 2020). "Finally, our results revealed an unexpected mechanism of Rac1 and Cdc42 deactivation in aggressive androgen-independent prostate cancer cells." (PMID 32092966, 2020). "Interestingly, consistent with our findings, miR-141 was demonstrated to suppress prostate cancer stem cells and metastasis by targeting cdc42 genes." (PMID 32925795, 2020). "To gain initial insights into the possible modulation of the CTD code by Rho signaling in human cells, we used the relatively specific inhibitors for RhoA, Rac and Cdc42 in two human cancer cell lines: the prostate cancer DU145 cell line, and the cervical carcinoma HeLa cell line." (PMID 32143485, 2020). "Increase in Cdc42 has been shown to increase MMP activity in prostate cancer cells." (PMID 28371345, 2017). "We therefore propose that a small-molecule inhibitor therapy targeting Rac1/Cdc42 Rho GTPase signaling pathways may be used as a novel treatment for patients with advanced prostate cancer." (PMID 24040362, 2013). "In support of this, our results suggest that PAK1 acts downstream of Rac and Cdc42 to promote actin polymerization, filopodia formation and cancer cell invasion, showing that F-actin reorganization plays a major role in cell movement in prostate cancer cells." (PMID 24040362, 2013). "We identified AZA1 as a novel Rac and Cdc42 inactivating compound with significantly improved inhibition of Rac combined with additional Cdc42 inhibitory activity when used in EGF-stimulated 22Rv1 prostate cancer cells." (PMID 24040362, 2013). "We propose that AZA1 could serve as a dual, Rac1 and Cdc42-targeting, small molecule inhibitor in the treatment of patients with advanced prostate cancer." (PMID 24040362, 2013). "Since PAK1 can also regulate cell transformation and survival and because of increased frequency of phosphorylation observed in poor outcome tumors, the PAK signaling pathway could therefore constitute a major effector pathway of Rac1/Cdc42 in prostate cancer cells." (PMID 24040362, 2013). "Moreover, AZA1-treatment also resulted in Rac1 and Cdc42 inhibition associated with suppression of cell proliferation in EGF-stimulated androgen-independent cell lines DU 145 and PC-3 in vitro, supporting the potential of AZA1 for use in prostate cancer." (PMID 24040362, 2013). "Through systematic analysis of nine high‐risk contaminants, we identified pan‐cancer targets and key pathway modules, with subsequent validation of hub genes (JUN, CDC42, MAPK14) in breast, colon, and prostate cancers using TCGA datasets." (PMID 41246859, 2025). "In summary, our work identified Rac1 and Cdc42 hyperactivation in aggressive androgen-insensitive DU145 and PC3 prostate cancer cell lines." (PMID 32092966, 2020). "Both RAC1-specific and dual RAC1/CDC42 inhibitors (NSC23766 and AZA1, respectively) have shown preclinical efficacy in prostate cancer cell lines (including PTEN-null PC-3 cells), inhibiting both cell migration and in vivo tumor growth." (PMID 33105713, 2020). "The small-molecule inhibitor ZCL278 that blocks CDC42–intersectin (ITSN) interactions and its more potent analogue ZCL367 that also inhibits RAC1 have shown preclinical promise in prostate cancer." (PMID 33105713, 2020). "In support, siRNA silencing of RAC/CDC42 regulating GEFs, such as PIP3-dependent Rac exchanger 1 (PREX1) and vav guanine nucleotide exchange factor 3 (VAV3), can significantly reduce prostate cancer cell proliferation and migration in vitro." (PMID 33105713, 2020).
prostate carcinoma (continued). "A number of RhoGEFs are overexpressed in prostate cancer, including Rac1 GEF P-Rex and Vav3 GEF for RhoA, Rac and CDC42, and are responsible for promoting metastasis and castration resistant prostate cancer (CRPC) by regulating androgen receptor (AR) activity." (PMID 30558664, 2018). "In contrast, incubation of prostate cancer cells with EPA and DHA reduced the protein expression of GTPases (rac1, rac2 and cdc42) (abstract only)]." (PMID 25971815, 2015). "Similarly, in the targeted treatment of prostate cancer with nintedanib, prostate cancer cells acquired resistance to nintedanib and survived by activating entosis formed by the upregulation of E-cadherin and ROCK1/2 through the PI3K/CDC42 signaling pathway." (PMID 37637068, 2023). "In human prostate carcinoma cells, TGF-β treatment induced a rapid formation of lamellipodia through the SMAD-independent signaling pathway, which requires the activation of the Rho-family GTPases including CDC42 and RHOA." (PMID 35151689, 2022). "Our data presented here outline the possibility that CdGAP/ARHGAP31, a negative regulator of Rac1 and Cdc42, acts as an oncoprotein rather than a tumor suppressor in prostate cancer." (PMID 34493786, 2021). "Their experiments also found that ZCL278 suppressed the activity of Cdc42 by directly binding to the molecule, and inhibited the migration of cultured prostate cancer cells from lines such as PC-3 but did not disrupt cell viability." (PMID 29596304, 2018). "Another Rac1 and Cdc42 dual-inhibitor, AZA1, identified from a screen of molecules based on modifying the structure of NSC23766, has been used in in vitro studies to target prostate cancer cells." (PMID 27104658, 2016). "This synthetic compound reduced cancer cell migration and proliferation and succeeded in increasing the survival of xenograft mouse models of prostate cancer by targeting Rac1 and Cdc42 but not RhoA." (PMID 27104658, 2016). "In contrast, AZA1 treatment caused no changes in phosphorylation of the potential Rac1 effectors ERK, JNK or p38 (data not shown), indicating that activation of these MAPK pathways is not affected by Rac1 and Cdc42 inhibition in 22Rv1 prostate cancer cells." (PMID 24040362, 2013). "Thus, the observed unchanged activity of p38 and JNK following Rac1/Cdc42-inhibition by AZA1 suggests that these pathways play no major role in mediating AZA1-induced anti-proliferative effects in 22Rv1 prostate cancer cells." (PMID 24040362, 2013). "Of interest, the tumor suppressor maspin has been reported to mediate tumor cell migration through inhibiting Rac1 and Cdc42, but not RhoA GTPase, suggesting that targeting the Rac1/Cdc42 pathways by AZA1 could counteract the activity of maspin in prostate cancer cells." (PMID 24040362, 2013). "Although the function of CDC42 is well documented, the involvement of CDC42 specific GEF FGD4 in prostate cancer has not been reported." (PMID 30558664, 2018). "In androgen-independent prostate cancer cells, AZA1 inhibited both Rac1 and Cdc42 but not RhoA GTPase activity in a dose-dependent manner and blocked cellular migration and proliferation." (PMID 24040362, 2013).
ovarian carcinoma (33 papers, 2010 to 2024). A malignant neoplasm originating from the surface ovarian epithelium. "Cdc42 is directly implicated in the regulation of cancer cell invasion, therefore we investigated the role of StarD13 in regulating the invasion of ovarian cancer cells." (PMID 34958986, 2022). "Despite evidence that elevated expression or activity of Rac1 is associated with worse prognosis in ovarian cancer, there is limited knowledge on the impact of Rac1 or Cdc42 inhibition in vivo." (PMID 33413202, 2021). "Genomic region 1p36.12 has been found to be associated with both endometriosis and ovarian carcinomas, and endometriosis risk alleles located within that locus have been described to act through inverse regulation of nearby genes such as CDC42 and LINC000339." (PMID 34199930, 2021). "Our own retrospective analyses demonstrate a benefit of racemic ketorolac in ovarian cancer patients and R-ketorolac inhibits Rac1 and Cdc42 GTPases and tumor associated behaviors of human ovarian tumor cells both in vivo and in vitro." (PMID 26558612, 2015). "CDC42 signaling in ovarian cancer has been associated with disease progression and is frequently overexpressed in primary ovarian tumors, though its association with compressive stimulation is still unknown." (PMID 32532057, 2020). "Among the Rho GTPases family, cell division control protein 42 (CDC42) is frequent overexpression in epithelial cancers, especially in ovarian cancers." (PMID 37511553, 2023). "In vitro: Fascin-1 silencing or pharmacological inhibition decreased cancer cell migration and impaired Cdc42 and Rac1 activityIn vivo: reduced ovarian cancer metastasis formation in mice." (PMID 37511011, 2023). "The results obtained support the tumor suppressor role of StarD13 and that StarD13 is a GAP for Cdc42 in ovarian cancer cell lines, as was previously shown in other tumor types." (PMID 34958986, 2022). "Ketorolac has a novel pharmacologic activity by inhibiting Rac1 and Cdc42, potentially contributes to the survival benefit in women with ovarian cancer and reduces ovarian cancer-specific mortality." (PMID 35154449, 2022). "This strongly suggests that StarD13 is a GAP for Cdc42 in ovarian cancer as it was shown in other tumor types." (PMID 34958986, 2022). "Ketorolac, a kind of Cdc42 specific inhibitor, can potentially contribute to the observed survival benefit in women after ovarian cancer surgery." (PMID 35154449, 2022). "To further understand the mechanism of StarD13 regulation of ovarian cancer invasion, we investigated the effects of StarD13 and Cdc42 inhibition on invadopodia formation." (PMID 34958986, 2022). "In ovarian cancer, we reported elevated Rac1 and Cdc42 protein levels in high grade vs. low grade tumors and elevated mRNA expression of a constitutively active splice variant Rac1b in low grade ovarian tumors." (PMID 33413202, 2021). "The treatment inhibited the actin-bundling into stress fibers as well as ovarian cancer cell migration by reducing GTP-bound Cdc42 and Rac1, further indicating a therapeutic role of G2 in ovarian cancer." (PMID 34830909, 2021). "This confirms previous reported studies, where eIF6 knockdown in CRC cells significantly reduced proliferation and colonogenicity, while eIF6 overexpression enhanced the migratory phenotype by augmenting CDC42 translation in ovarian cancer." (PMID 34016142, 2021). "Taken together, these studies support potential benefits of inhibiting Rac1 and/or Cdc42 in ovarian cancer." (PMID 33413202, 2021). "The human equivalent dose of R-ketorolac partially inhibited Rac1 and Cdc42 and the magnitudes of inhibition were similar to those measured in samples from ovarian cancer patients who received the racemic drug." (PMID 33413202, 2021). "Nevertheless, the R-enantiomer of the common NSAID ketorolac was repurposed in ovarian cancer cells to decrease Cdc42 dependent filopodia formation and cell migration." (PMID 32503267, 2020).
ovarian carcinoma (continued). "A published study showed that R-enantiomer of the anti-inflammatory drug ketorolac inhibited Rac1 and Cdc42 and showed a better outcome in ovarian cancer treatment." (PMID 32443784, 2020). "When CDC42 inhibition was combined with dual drug treatment, the ovarian cancer cell proliferation was significantly decreased, and cell death was enhanced beyond chemotherapeutics or inhibitor use alone." (PMID 32532057, 2020). "Inhibition of Rac1 and Cdc42 in ovarian cancer patients can be achieved by the administration of racemic ketorolac, a mix of the R- and S-enantiomers." (PMID 32443784, 2020). "CID2950007 (ML141) and CID44216842 specifically target Cdc42 and restrict the motility of ovarian cancer cells." (PMID 32503267, 2020). "R-naproxen demonstrated the same activities against Rho-family GTPases Rac1 and Cdc42 as R-ketorolac in immortalized ovarian cancer (OvCa429, OvCa433) and cervical cancer (HeLa T4+) cells." (PMID 32443784, 2020). "This prediction was supported by the finding of time-dependent inhibition of Rac1 and Cdc42 activity in cells retrieved from the peritoneal compartment of these post-surgical ovarian cancer patients after ketorolac administration." (PMID 31344967, 2019). "The current status of the literature indicates that both classes of targets (COXs and Rac1/Cdc42 GTPases) are important in ovarian cancer progression, metastasis, and patient outcome." (PMID 31344967, 2019). "Clinical trials using R-ketorolac alone would offer an opportunity to directly test the predicted benefit of a Rac1/Cdc42-selective inhibitor in ovarian cancer patients." (PMID 31344967, 2019). "The R enantiomer of ketorolac, (ketorolac is given as an anti-inflammatory drug), can inhibit Rac1 and Cdc42 and was shown to improve patient outcomes in treatment for ovarian cancer." (PMID 27104658, 2016). "Given that Rac1 and Cdc42 are highly expressed and active in ovarian cancer, inhibitors of these 2 GTPases have been tested in immortalized and primary human ovarian cancer cells." (PMID 27104658, 2016). "Evaluation of Gα13-specific signalingpathways in SKOV3 or HeyA8 ovarian cancer cell lines indicate that Ric-8Apotentiates Gα13-mediated activation of RhoA, Cdc42, and thedownstream p38MAPK." (PMID 27096001, 2015). "Overexpressed Trip10 was associated with endogenous Cdc42 and huntingtin in IMR-32 brain tumor cells and CP70 ovarian cancer cells." (PMID 21299869, 2011). "In addition, Cdc42 depletion completed abolished matrix degradation in control ovarian cancer cells." (PMID 34958986, 2022). "Regarding the for downstream regulation of eIF6, existing studies have demonstrated that eIF6 could indirectly regulate Wnt/-catenin signaling in CRC cells and affect CDC42 signaling in ovarian cancer cells, which promotes migration and invasion." (PMID 34016142, 2021). "Given the upregulation of CDC42 observed under compressive stimulation, we hypothesized that the phenotypic changes observed in ovarian cancer cells under compression rely on CDC42 activity." (PMID 32532057, 2020). "Additionally, ovarian cancer cells upregulate CDC42 significantly and consistently across high grade serous cell types and compressive stimulation type (static or cyclic)." (PMID 32532057, 2020). "Additionally, elevated expression and activity of Rac1 and Cdc42 was detected in tissues of ovarian cancer patients." (PMID 32443784, 2020). "In addition, pitavastatin alters the subcellular localization of RhoA, CDC42 and Ras in several ovarian cancer cell lines." (PMID 32727400, 2020). "Besides, Cdc42 knockdown significantly reduced cell proliferation and notably inhibited the adhesion, motility and invasiveness in ovarian cancer." (PMID 30795761, 2019). "However, our findings correlate well with CDC42 and RhoB expression levels found in the Ovarian cancer database of Cancer Science Institute Singapore (CSIOVDB), reporting significantly higher CDC42 and RhoB levels in OCCC compared to the other subtypes." (PMID 28611940, 2017).
ovarian carcinoma (continued). "Furthermore, it has recently been shown that activation of the PI3K/Akt pathway, known to be upstream of Rac1 and Cdc42 activity, positively correlates with uPA expression in an ovarian cancer cell line." (PMID 20067638, 2010). "Moreover, ovarian cancer is characteristically metastatic and cdc42 has been speculated to be accountable for the migratory phenotype." (PMID 25886394, 2015). "Thus, we investigated whether eIF6 over-expression could induce the activation of cdc42-Pak signalling in A2780 ovarian cancer cells." (PMID 25886394, 2015). "DOCK7 has also been reported to be highly expressed in ovarian cancer, and is recruited into the nucleus by MDC1 to participate in the DNA damage response through the RAC1/CDC42/PAK1 module." (PMID 38385857, 2024). "In ovarian cancer, RHGAP10 inhibits Cdc42 activity in cells, in turn, it can inhibit the growth and invasion of tumors, thus playing a role in cancer suppression." (PMID 38041020, 2023). "Next, we chose siRNA CDC42 and blebbistatin, the myosin II ATPase inhibitor, to investigate the role of the CDC42/PAK/MLC2 signaling pathway in regulating ovarian cancer cell stiffness." (PMID 37511553, 2023). "In this study, we investigate the potential role of the Cdc42 GAP StarD13 in the modulation of cell motility, invasion in ovarian cancer cells." (PMID 34958986, 2022). "In ovarian cancer cells, StarD13 depletion also led to an increase in cortactin-labeled and WASP-labeled potential invadopodia, while Cdc42 depletion completed abolished any of these structures." (PMID 34958986, 2022). "Specific CDC42 inhibition, through ML141 treatment, also significantly reduced the ovarian cancer cell proliferation and increased cancer cell death for both control and compressive stimulations." (PMID 32532057, 2020). "Rac1 and Cdc42 are highly expressed in EOC and therefore inhibitors of these two GTPases have undergone research on primary human ovarian cancer cells." (PMID 32443784, 2020). "In ovarian cancer cells, p70-S6K1 regulates cytoskeleton organization and cell migration by activating the GTPases Rac1 and Cdc42, involved, respectively, in dictating forward movement and migration’s direction." (PMID 27491285, 2016). "Using quantitative PCR with reverse transcription (RT–qPCR) analysis we quantified expression of HOXD9, CDC42 and CDCA8 in ovarian cancer cell lines (N=14) and ovarian (N=6) and fallopian (N=3) epithelial cells." (PMID 26391404, 2015). "In conclusion, we have demonstrated that MCAM have multiple effects on epithelial ovarian cancer cell properties, including invasion, apoptosis and spreading on extracellular matrix, which may be related to the dysregulation of small Rho GTPase (RhoA and Cdc42)." (PMID 22610942, 2012). "R-ketorolac inhibitor was identified in a study on immortalized human ovarian adenocarcinoma cells (SKOV-3ip) and primary patient-derived ovarian cancer cells with similar effects to those of small molecule inhibitors of Rac1 (NSC23766) and Cdc42 (CID2950007/ML141)." (PMID 32443784, 2020). "Compared to human normal ovarian surface epithelial cells (HOSE), CDC42-v2 was indeed downregulated in these immortalized cells and ovarian cancer cell lines (left side) but the expression of CDC42-v1 was not significantly different (data not shown)." (PMID 26336992, 2015). "We reported previously that R-ketorolac, but not the S-enantiomer, inhibited Rac1 and Cdc42-dependent downstream signaling, growth factor stimulated actin cytoskeleton rearrangements, cell adhesion, migration and invasion in ovarian cancer cell lines and patient-derived tumor cells." (PMID 33413202, 2021). "However, the role of CDC42 in ovarian cancer compressive stress induced mechanotransduction was not identified before this report." (PMID 32532057, 2020).
ovarian carcinoma (continued). "Taken together, our identification of R-ketorolac as a Rac1/Cdc42 GTPase inhibitor may help to explain the apparent benefits of racemic ketorolac in human breast and ovarian cancer patient survival, and why other NSAIDs have not yielded comparable findings." (PMID 31344967, 2019). "Whether or not myosin II is regulated by CDC42 in ovarian cancer cells has not been investigated." (PMID 37511553, 2023). "ML141 has been demonstrated to be a potent, selective and reversible non-competitive inhibitor of Cdc42 activation in MDA-MB-231 cells, human ovarian carcinoma cell lines (OVCA429 and SKOV3ip), and pancreatic cancer cell lines (BxPC-3, Panc-1 and HPAF II)." (PMID 33499191, 2021).